OR2L13 (olfactory receptor family 2 subfamily L member 13)
Description:
Odorant receptor.
Synonyms: OR2L14
Tractability: Antibody: its Gene Ontology location is reachable by antibodies, with high confidence; UniProt places it where antibodies can reach, with medium confidence; UniProt predicts a signal peptide or a membrane-spanning region.
Gene: Protein-coding gene on chromosome 1 (248,095,184 to 248,101,163, forward strand). Ensembl gene ENSG00000196071.
Subcellular location: Cell membrane
Pathways (Reactome):
Sensory Perception: Expression and translocation of olfactory receptors; Olfactory Signaling Pathway
Gene Ontology:
Molecular function: protein binding; olfactory receptor activity; G protein-coupled receptor activity
Biological process: detection of chemical stimulus involved in sensory perception of smell; G protein-coupled receptor signaling pathway
Cellular component: plasma membrane; membrane
Genetic constraint (gnomAD): Loss-of-function variants: 14 observed, 16.05 expected, observed/expected ratio (o/e) 0.87, 90% interval 0.57 to 1.36. The upper end of that interval is the gene's LOEUF score, 1.36, which puts it in group 5 of 6, group 1 being the genes least tolerant of losing a copy. Missense variants: 356 observed, 397.82 expected, observed/expected ratio (o/e) 0.89, 90% interval 0.82 to 0.98. Synonymous variants: 144 observed, 145.92 expected, observed/expected ratio (o/e) 0.99, 90% interval 0.86 to 1.13.
Homologues: Orthologues: chimpanzee OR2L13 (99% identical), mouse Or2l13 (84% identical), mouse Or2l13b (84% identical), rat Or2l13 (84% identical), rat Or2l13c (82% identical), rabbit OR2L13 (81% identical). Paralogues in human: OR2L2 (71% identical), OR2L5 (71% identical), OR2L3 (71% identical), OR2L8 (70% identical), OR2AJ1 (53% identical), OR2AK2 (53% identical), OR2M3 (52% identical), OR2M5 (52% identical), OR2M2 (51% identical), OR2T1 (51% identical), OR2M7 (50% identical), OR2T33 (50% identical), and 80 more.
Diseases named in the same sentence as OR2L13 in open-access papers:
OR2L13 is named in the same sentence as 12 diseases in open-access papers, as found by Europe PMC text mining. Sharing a sentence is not in itself a finding about the gene and the disease. The quoted sentences say what the papers report.
autism spectrum disorder (3 papers, 2021 to 2024). A spectrum of developmental disorders that includes autism, and Asperger syndrome. "One DMR was located in the promoter of OR2L13 which has been associated with autism spectrum disorders, and the other was located in the gene body of CYP2E1 which has been implicated in type 1 and type 2 diabetes." (PMID 35721735, 2022).
aortic aneurysm (2 papers, 2022 to 2024). A ruptured aneurysm located in the wall of the proximal portion of the descending aorta proceeding from the arch of the aorta. "The latest study did find evidence for olfactory receptor 2L13 (OR2L13) in growth of aortic aneurysms (AAA)." (PMID 39054468, 2024). "Among them, rs34508376 (OR2L13) was a suggestive role in CeAD pathophysiology which was in line with the previous observations in aortic aneurysms." (PMID 39054468, 2024). "This discovery was made in aortic aneurysmal disease where platelet OR2L13 appears to be upregulated in response to biomechanical activation and, specifically, by external D-flow exposure." (PMID 35324479, 2022). "When platelet OR2L13 was activated during AAA development by an exogenous, activating ligand, the biological consequence was suppression of platelet and aortic MMP activity, limiting aortic aneurysm progression." (PMID 35324479, 2022).
glioma (1 paper, 2024). A benign or malignant brain and spinal cord tumor that arises from glial cells (astrocytes, oligodendrocytes, ependymal cells). "Consistently, OR2L13 showed significant up-regulation in recurrent tumors in the Glioma Longitudinal AnalySiS (GLASS) dataset." (PMID 39769144, 2024).
Parkinson disease (1 paper, 2017). A progressive degenerative disorder of the central nervous system characterized by loss of dopamine producing neurons in the substantia nigra and the presence of Lewy bodies in the substantia nigra and locus coeruleus. "In this context, OR2L13 is not only expressed in brain, it is also dysregulated in Parkinson’s disease." (PMID 28174521, 2017).
thrombotic disease (1 paper, 2022). The formation of a blood clot in the lumen of a vessel or heart chamber; causes include coagulation disorders and vascular endothelial injury. "OR2L13 activators are therefore foundational to a new class of antiplatelet agents for thrombotic diseases." (PMID 35324479, 2022).
cancer (1 paper, 2022). A tumor composed of atypical neoplastic, often pleomorphic cells that invade other tissues. "In order to verify reliable GRSDMs, 22 specific DNA methylation genes related to prognosis obtained in the training set were verified on 11 sets of GEO data, and 8 of the specific DNA methylation genes (DGRK, F2RL3, GRK5, NECAB2, OR1C1, OR2L13, OR6F1, and PIK3R6) had been verified in pan-cancer." (PMID 35885996, 2022).
cardiovascular disease (1 paper, 2022). "OR2L13 agonists could be alternative antiplatelet agents for patients with cardiovascular disease in whom P2Y12 receptor antagonists are ineffective." (PMID 35324479, 2022).
tumor (1 paper, 2024). "This expression pattern provides novel insights into treatment-induced neuronal transition and GBM recurrence mechanisms, suggesting that OR2L13-mediated synaptic regulation could be crucial for preventing tumor recurrence." (PMID 39769144, 2024). "OR2L13 was identified as a significantly down-regulated OR gene in GBM compared to normal and LGG tissues, with cell-type-specific expression analysis revealing its predominant expression in oligodendrocytes and neurons rather than tumor cells." (PMID 39769144, 2024).
OR2L13 also shares sentences with these, for which no sentence is quoted: type 2 diabetes (2 papers); aneurysm (1); autism (1); neurodevelopmental disorder (1).